SLCO3A1 (solute carrier organic anion transporter family member 3A1)
Description:
Putative organic anion antiporter with apparent broad substrate specificity. Recognizes various substrates including thyroid hormone L-thyroxine, prostanoids such as prostaglandin E1 and E2, bile acids such as taurocholate, glycolate and glycochenodeoxycholate and peptide hormones such as L-arginine vasopressin, likely operating in a tissue-specific manner. The transport mechanism, its electrogenicity and potential tissue-specific counterions remain to be elucidated (Probable). Mediates transport of tryptophan, phenyalanine and tyrosine. [Isoform 1]: Mediates transport of steroid hormone precursors dehydroepiandrosterone 3-sulfate and estrone 3-sulfate. [Isoform 2]: Mediates transport of steroid hormone precursors dehydroepiandrosterone 3-sulfate and estrone 3-sulfate. [Isoform 5]: Mediates transport of steroid hormone precursors dehydroepiandrosterone 3-sulfate and estrone 3-sulfate.
Synonyms: OATP3A1; OATP-RP3; OATPRP3; OATP-D; OATPD; SLC21A11
Tractability: Antibody: UniProt places it where antibodies can reach, with high confidence; its Gene Ontology location is reachable by antibodies, with high confidence; UniProt predicts a signal peptide or a membrane-spanning region.
Target class: Electrochemical transporter; SLC superfamily of solute carriers; SLC21/SLCO family of organic anion transporting polypeptides; Transporter
Gene: Protein-coding gene on chromosome 15 (91,853,708 to 92,172,435, forward strand). Ensembl gene ENSG00000176463.
Subcellular location: Basolateral cell membrane (Isoform 1); Apical cell membrane (Isoform 2); Basal cell membrane; Apical cell membrane (Isoform 5)
Pathways (Reactome):
Transport of small molecules: Organic anion transport by SLCO transporters
Gene Ontology:
Molecular function: prostaglandin transmembrane transporter activity; transmembrane transporter activity; secondary active transmembrane transporter activity
Biological process: phenylalanine transport; positive regulation of canonical NF-kappaB signal transduction; positive regulation of MAPK cascade; prostaglandin transport; tryptophan transport; tyrosine transport; sodium-independent organic anion transport; transport across blood-brain barrier; transmembrane transport
Cellular component: apical plasma membrane; basal plasma membrane; basolateral plasma membrane; plasma membrane; membrane
Genetic constraint (gnomAD): Loss-of-function variants: 24 observed, 52.93 expected, observed/expected ratio (o/e) 0.45, 90% interval 0.33 to 0.64. The upper end of that interval is the gene's LOEUF score, 0.64, which puts it in group 2 of 6, group 1 being the genes least tolerant of losing a copy. Missense variants: 735 observed, 879.03 expected, observed/expected ratio (o/e) 0.84, 90% interval 0.79 to 0.89. Synonymous variants: 453 observed, 388.83 expected, observed/expected ratio (o/e) 1.16, 90% interval 1.08 to 1.26.
Homologues: Orthologues: chimpanzee SLCO3A1 (99% identical), mouse Slco3a1 (98% identical), macaque SLCO3A1 (94% identical), rat Slco3a1 (93% identical), pig SLCO3A1 (93% identical), dog SLCO3A1 (93% identical), guinea pig SLCO3A1 (90% identical), tropical clawed frog slco3a1 (87% identical), rabbit SLCO3A1 (83% identical), zebrafish slco3a1a (76% identical), zebrafish slco3a1b (73% identical), Drosophila melanogaster Oatp30B (37% identical). Paralogues in human: SLCO5A1 (34% identical), SLCO1C1 (32% identical), SLCO1B3 (31% identical), SLCO1A2 (31% identical), SLCO2A1 (31% identical), SLCO1B1 (30% identical), SLCO4C1 (29% identical), SLCO2B1 (29% identical), SLCO4A1 (28% identical), SLCO6A1 (22% identical).
Diseases named in the same sentence as SLCO3A1 in open-access papers:
SLCO3A1 is named in the same sentence as 34 diseases in open-access papers, as found by Europe PMC text mining. Sharing a sentence is not in itself a finding about the gene and the disease. The quoted sentences say what the papers report.
nicotine dependence (3 papers, 2014 to 2023). Physical and psychological dependence on nicotine. "Since smoking is known to be an aggravating factor for CD and SLCO3A1 was reported to be associated with nicotine dependence, we evaluated the effect of nicotine on NF-κB activation in cells overexpressing SLCO3A1." (PMID 24945726, 2014). "Additionally, a genome-wide association study identified SLCO3A1’s involvement in nicotine dependence, highlighting its relevance to addiction." (PMID 37759782, 2023). "There is suggestive evidence that SLCO3A1 may be associated with nicotine dependence and blood pressure through interaction with smoking." (PMID 33937227, 2021). "A recent meta-analysis of GWAS showed that SLCO3A1 is associated with nicotine dependence." (PMID 24945726, 2014). "Meta-analyses of GWAS have also shown that SLCO3A1 is associated with nicotine dependence." (PMID 24945726, 2014).
Obesity (3 papers, 2021 to 2025). Accumulation of substantial excess body fat. "In ovarian granulosa cells of rats with polycystic ovary syndrome (PCOS), SLCO3A1 mRNA expression was significantly higher than in normal cells, suggesting its potential role in lipid metabolism and obesity-related conditions." (PMID 40149398, 2025).
cholestasis (2 papers, 2021 to 2024). Impairment of the bile flow caused by obstruction within the liver, or outside the liver in the bile duct system. "SLCO3A1 (OATP3A1) is upregulated in the liver during cholestasis and contributes to the elimination of the bile acids that accumulate in the liver." (PMID 34884954, 2021).
Crohn disease (2 papers, 2014 to 2023). A gastrointestinal disorder characterized by chronic inflammation involving all layers of the intestinal wall, noncaseating granulomas affecting the intestinal wall and regional lymph nodes, and transmural fibrosis. "Not long ago, the OATP3A1 encoding gene (SLCO3A1) was identified as a novel Crohn’s disease-associated gene." (PMID 36985493, 2023).
depression (2 papers, 2012 to 2023). "An association study of 15q25-26 for recurrent early onset depression showed nominal association with NTRK3 and the genes flanking ST8SIA2: SLCO3A1 and C15orf32; but not ST8SIA2 itself." (PMID 22693595, 2012).
epilepsy (2 papers, 2023). A brain disorder characterized by episodes of abnormally increased neuronal discharge resulting in transient episodes of sensory or motor neurological dysfunction, or psychic dysfunction. "The deletion of SLCO3A1 fragments has been strongly linked to Angelman syndrome (AS), a severe cognitive disorder characterized by ataxia, epilepsy and abnormal behavior." (PMID 37759782, 2023). "Several candidate genes for epilepsy include calmodulin-regulated spectrin-associated protein 1-like protein 1 (CAMSAP1L1), glutamate metabotropic receptor 3 (GRM3), CD3 gamma subunit of T-cell receptor complex (CD3G), and solute carrier organic anion transporter family member 3A1 (SLCO3A1)." (PMID 37246165, 2023).
ovarian carcinoma (2 papers, 2018 to 2022). A malignant neoplasm originating from the surface ovarian epithelium. "Since ovarian cancer cells express mesenchymal and epithelial markers simultaneously, transition from one state to another might be a continuous process in these cells, for which SLCO3A1 might be a marker." (PMID 30131693, 2018). "Different from the four SLCO genes (SLCO3A1, 2A1, and 2B1) with high expression in mesothelial cells, we identified SLCO4A1 having higher levels in a group of ovarian cancer cell lines compared with mesothelial cells." (PMID 36105223, 2022). "Notably, ubiquitously expressed SLCO2A1, SLCO2B1, SLCO3A1, and SLCO4A1 genes have been identified in ovarian cancer." (PMID 30131693, 2018).
acute respiratory distress syndrome (1 paper, 2021). Progressive and life-threatening pulmonary distress in the absence of an underlying pulmonary condition, usually following major trauma or surgery. "In particular, the expression of circRNA Slco3a1 was significantly increased and circRNA Wdr33 was markedly reduced in patients with acute respiratory distress syndrome." (PMID 35141166, 2021).
aneurysmal bone cyst (1 paper, 2020). A locally aggressive and destructive benign cystic lesion of the bone. "As for SLCO3A1, SLCO4A1 expression appears to be increased in aneurysmal bone cysts and liver cancers, BCs and prostate cancers." (PMID 32388639, 2020).
cervical cancer (1 paper, 2022). A primary or metastatic malignant neoplasm involving the cervix. "Rs11853125 is located at the region between Cervical Cancer-Associated Transcript 37 (CRAT37) and Solute Carrier Organic Anion Transporter Family Member 3A1 (SLCO3A1)." (PMID 35299963, 2022).
colorectal cancer (1 paper, 2014). A primary or metastatic malignant neoplasm that affects the colon or rectum. "Next, we compared SLCO3A1 mRNA expression in normal and non-CD diseases (colorectal cancer for colonic expression and reperfusion inflammation for small intestine expression) with CD patients." (PMID 24945726, 2014).
glioma (1 paper, 2012). A benign or malignant brain and spinal cord tumor that arises from glial cells (astrocytes, oligodendrocytes, ependymal cells). "We excluded four genes (SLCO3A1, C10orf11, PTPRJ, and NMNAT1) from further analysis because the direction of association of additional tested SNPs with glioma risk was inconsistent with our hypothesis." (PMID 23091480, 2012).
Infertility (1 paper, 2024). "In line with this, we found that numerous infertility-related DMR-associated genes are expressed during spermatogenesis (e.g., VPS37D, FAM9B [MIM: 300478], SLCO3A1, and CCDC200)." (PMID 38759652, 2024).
prediabetes (1 paper, 2022). "We found two susceptibility loci in MRPS6/SLC5A3 genes associated with 2hPG, six loci in LINC01648, MATN1, CRAT37, and SLCO3A1 genes associated with HbA1C, and five loci in TRPM3/TMEM2 and MLYCD/OSGIN1 correlated to BMI in Hainan prediabetes." (PMID 35299963, 2022).
primary hypertrophic osteoarthropathy (1 paper, 2022). A genetically and clinically heterogeneous inherited disorder characterized by digital clubbing and osteoarthropathy, with variable features of pachydermia, delayed closure of the fontanels, and congenital heart disease. "SLCO3A1 is an organic anion transporter that participates in the transport of non‐nucleoside reverse transcriptase inhibitor (NRTI) across the membrane, which is associated with human diseases including intestinal perforation and primary hypertrophic osteoarthropathy." (PMID 35299963, 2022).
cancer (5 papers, 2016 to 2020). A tumor composed of atypical neoplastic, often pleomorphic cells that invade other tissues. "SLCO3A1 has been detected in several cancers including breast, lung, colon, ovary and pancreas." (PMID 32388639, 2020). "The data indicated that all analyzed SLCO genes exhibited significantly increased expression levels (and/or were more often detectable) in cancer compared with benign tissue samples (FDR ranging from 0.038 for SLCO2B1 to 5.3 × 10−12 for SLCO3A1 and SLCO4A1, respectively)." (PMID 30131693, 2018).
female reproductive diseases (1 paper, 2024). "This suggested that targeting SLCO3A1 could be a potential strategy for treating female reproductive diseases." (PMID 38473715, 2024). "In conclusion, the knockdown of DNMT1 upregulated the mRNA and protein levels of SLCO3A1, thereby promoting the proliferation of GCs to facilitate the growth and development of ovarian follicles, and these results provide new insights into investigations of female reproductive diseases." (PMID 38473715, 2024).
mental illness (1 paper, 2023). "Considering the pivotal role of SLCO3A1 in neurodevelopment and mental illness, we hypothesize that it holds regulatory potential in the context of aggressive behavior in pigs." (PMID 37759782, 2023).
SLCO3A1 also shares sentences with these, for which no sentence is quoted: breast carcinoma (4 papers); Tumor (2); alcohol dependence (1); Alzheimer disease (1); Angelman syndrome (1); Anxiety (1); Ataxia (1); cognitive disorder (1); COVID-19 (1); follicular disorders (1); gastric cancer (1); liver cancer (1); peripheral neuropathy (1); polycystic ovary syndrome (1); prostate carcinoma (1); retinal diseases (1).